CGAS (cyclic GMP-AMP synthase)
Diseases named in the same sentence as CGAS in open-access papers (continued):
Sharing a sentence is not in itself a finding about the gene and the disease.
tumor (continued). "cGAS and STING expression in tumour cells might have a predictive potential for successful immunotherapy in patients with MSI-H stage IV CRC and future prospective studies should evaluate these findings." (PMID 36612217, 2022). "The cGAS-STING pathway-induced Type-1 interferon response drives the expression of multiple chemokines such as CXCL9, CXCL10, and CCL5, that act as chemical gradients to direct CTLs into the tumor tissue." (PMID 36353640, 2022). "The role of different tumor-derived type I IFNs during cancer progression has remained unclear, with most attention given to IFN secretion by immune cells or the regulation of Ifna/b genes downstream of cGAS-STING signaling." (PMID 36344707, 2022). "For instance, cGAS-STING pathway activation with antigen-presenting cells leads to production of Tap2 and MHC-I, which may enhance the tumor immune surveillance." (PMID 33843442, 2021). "Activating the cGAS-STING pathway can enhance the immune response and restrain tumor growth." (PMID 34867409, 2021). "Thus, it is possible that cGAS-STING stimulation contributes to antitumor immunity in both tumor and host immune cells indicating that TREX1, cGAS, and STING are candidate targets to modulate antitumor immunity." (PMID 33868310, 2021). "Few studies have suggested that certain regulatory factors are induced in response to cGAS-STING pathway activation, which could potentially attenuate the anti-tumor efficacy of STING agonists and lead to treatment resistance." (PMID 34070756, 2021). "Further, as discussed in detail in subsequent sections, in addition to tumor intrinsic mechanisms of cytotoxicity, PARPi trigger activation of the cyclic GMP–AMP (cGAMP) synthase (cGAS)— stimulator of interferon genes (STING) pathway inducing anti-tumor immunity." (PMID 34572943, 2021). "cGAS−/−, STING−/− and TLR3−/− mice showed similar tumor reduction as C57BL/6 WT animals after three treatments with intratumoral BCG, discarding the importance of these receptors in BCG-induced tumor regression." (PMID 34341449, 2021). "The DNA of tumor cells is commonly released in the process of rapid proliferation and antitumor therapy; subsequently, cGAS recognizes the DNA source and responds quickly to activate STING and downstream cascade reaction to eliminate tumor cells through innate immune response." (PMID 35265630, 2021). "Subsequently, autophagy induced by the cGAS–STING pathway plays crucial roles in balancing innate immune responses, maintaining intracellular environmental homeostasis, alleviating liver injury, and limiting tumor growth and transformation." (PMID 34948027, 2021). "There is a substantial body of literature detailing the role of cGAS/STING and other TLRs in the regulating the anti-tumor response to DNA-damaging therapies primarily through control of the adaptive immune response ultimately leading to CD8+ T-cell-mediated tumor cell death." (PMID 34884568, 2021). "If tumor-derived DNA were not degraded, the cGAS-STING pathway would be activated to promote IFN-dependent antitumor immunity." (PMID 33868310, 2021). "The activated cGAS-STING signal pathway would induce interferon (IFN) production to promote DCs maturation and activation, which mediated CD8+ T cells activation to provide tumor regression." (PMID 34956229, 2021). "Additionally, it was found that autophagy induced by the cGAS–STING pathway exerts a protective role in liver cancer, limiting transformation and tumor growth." (PMID 34948027, 2021). "While inhibition of cGAS/STING and PKR can provide an opportunity for Δγ134.5 oncolytic replication, early evidence regarding first-generation oHSV such as HSV1716, R3616, and G207 show a wide range of replication efficiencies across tumor types." (PMID 34372614, 2021). "At the same time, whether the cGAS-STING signal pathway is related to radiotherapy and chemotherapy, and whether it can be combined to play an effective anti-tumor effect, has attracted more and more attention from researchers." (PMID 34956229, 2021).
tumor (continued). "The current study found that cGAS and IRF3 played important roles in the inhibition of tumor growth by paclitaxel, combining an agonist of the cGAS-STING signaling pathway with paclitaxel could significantly improve the efficacy." (PMID 34483930, 2021). "The appearance of DNA in the cytoplasm can drive Cyclic GMP-AMP Synthase-2′,3′-Cyclic Guanosine Monophosphate–Adenosine Monophosphate-Stimulator of Interferon Genes (cGAS-cGAMP-STING) inflammatory, anti-tumour T-cell activity via a type I interferon (IFN) and nuclear factor-κB response." (PMID 35006469, 2021). "Using cGAS (cGAS−/−) and STING (Tmem173−/−) deficient mice, researchers confirmed that deletion of the pathway-related genes in mice caused complete loss of anti-tumor responses with no increased CD8+ or CD4+ TILs after Mn2+ administration." (PMID 34956229, 2021). "The emerging lines of evidence show that the cGAS/STING pathway performs positive facilitation on immune response in tumors; nevertheless, current studies propose a potential promotion of this pathway in tumor initiation, progression, and metastasis." (PMID 35265630, 2021). "In addition, cGAS/STING pathway activation has also been indicated to regulate intrinsic cellular programs, including inducing tumor cell autophagy, apoptosis, necroptosis, and pyroptosis." (PMID 35265630, 2021). "Accumulating data had demonstrated that activation of the cGAS-STING pathway is crucial in the TME, and the benefit of induced tumor regression and increased survival time in preclinical studies and clinical trials had been achieved by STING agonists administration." (PMID 34625078, 2021). "Considering the key role of the cGAS-STING signal pathway and related TAMs in anti-tumor immunity, many studies have explored whether the related STING agonists could exert strong anti-tumor effects via regulating TAMs polarization." (PMID 34956229, 2021). "Indeed, this approach induces accumulation of inflammatory cytosolic nucleic acids, leading to cGAS-STING pathway activation and promoting T cell infiltration and thus tumor regression." (PMID 33981307, 2021). "Mechanistically, the cGAS/STING pathway was activated by STING agonist in endothelial cells instead of DCs and other immune cells, thus promoting the trafficking and infiltration of CD8+ T cells into tumor." (PMID 35265630, 2021). "cGAS/STING pathway activation in tumor cells forms an obstacle to the early-stage tumors through upregulating IFN-I and inflammatory cytokines for antitumor immunity, which is also closely related to induction of tumor cell senescence." (PMID 35265630, 2021). "All above results suggested the cGAS-STING pathway, as a cytosolic DNA-sensing pathway, played the potential contribution of anti-tumor efficiency through mediating the recruitment, activation, and differentiation of CD4+ and CD8+ T cells, especially the CD8+ T cells." (PMID 34956229, 2021). "In contrast, hypofractionated RT (8 Gy/day on three consecutive days) did not induce Trex1 and, therefore, promoted stronger cGAS-STING activity as well as higher expression of IFN-β in tumor cells." (PMID 34830176, 2021). "Then, the excessive tumor cell-derived DNA could significantly activate the cGAS-STING signal pathway of DCs to strengthen antigen presentation and the activation and differentiation of CD8+ T cells to exert corresponding anti-tumor effects." (PMID 34956229, 2021). "Importantly genetic depletion of tumor cGAS–STING abolished the CD8+ adaptive immune response and anti-tumor activity of olaparib." (PMID 34884568, 2021). "However, caution needs to be exercised when using STING inhibitors in AGS patients because, as detailed in the previous section, disruption of cGAS and STING suppresses spontaneous anti-tumor immune surveillance." (PMID 33717156, 2021). "cGAS/STING pathway in cancer settings is under deep examination in both tumor cells as well as in neighboring immune and non-immune cells." (PMID 34659260, 2021).
tumor (continued). "Conversely, cGAS expression by host immune cells is not necessarily required, suggesting that tumor-derived cGAMP is transferred to non-tumor cells where it activates STING." (PMID 34079557, 2021). "However, it is worth noting that there have been several lines of evidence that suggest that chronic activation of SASP or cGAS–STING signaling leads to a phenotype of immunosuppression, increased tumor progression, and metastasis." (PMID 34884568, 2021). "More general, the therapeutic induction of an immunogenic form of tumor cell death will not be achieved by a combination of H-1PV with gemcitabine-like drugs which employ cGAS/STING/TBK1-mediated signaling to trigger IFN production." (PMID 34071585, 2021). "Moreover, our data demonstrate that PARPi modulates the TME by activating the cGAS-STING pathway, thereby altering the balance of immunostimulatory signaling and enabling low-dose CAR-T cell treatment to induce effective tumor regression." (PMID 34556152, 2021). "The resulting cGAS-STING pathway activation promotes maturation and cross-presentation, ultimately leading to the recruitment and the infiltration of cytotoxic CD8(+) T cells at the tumor site." (PMID 33981307, 2021). "In this way, metastatic cells can exploit the pro-metastatic effects of cGAS-STING signalling without triggering an anti-tumour type I IFN response." (PMID 33731858, 2021). "A growing body of studies has found that the activation of the cGAS-STING signal pathway in TAMs is related to TAMs polarization that is necessary for bridging innate and adaptive immune responses, thereby regulating the tumor progression." (PMID 34956229, 2021). "Tumor-derived DNA captured by cGAS in DCs as well as tumor cells themselves in tumor microenvironment (TME) is the primary driving force to activate STING signaling to induce the production of type I IFN and the tumor-specific CD8+ T cell priming." (PMID 33485379, 2021). "Thus, while current studies support cGAS-STING function in antitumor immunity following radiotherapy and/or chemotherapy, the precise nature of cGAS and STING’s roles in tumor and immune-cell function remain unresolved." (PMID 33868310, 2021). "Transient cGAS-STING activation in innate immune cells may display anti-tumor activity, whereas sustained activation might induce immune tolerance and tumor growth." (PMID 34659260, 2021). "Here, we review the molecular mechanisms and activation of the cGAS/STING pathway, and the relationship between DNA damage and this pathway, particularly highlighting the remodeling of immune contexture in tumor environment (TME) triggered by cascade inflammatory signals." (PMID 35265630, 2021). "Accordingly, cGAS/STING activation pathway may exert either an antitumour or pro-tumour effect, depending on several factors, such as the stage of tumour progression and the tissue-specific context." (PMID 34885119, 2021). "As opposed to non-malignant cells, tumor cells have a propensity to contain cytosolic DNA where it is in turn recognized by cGAS given its affinity for dsDNA in a sequence-independent manner." (PMID 34884568, 2021). "The activation of cGAS-STING pathway boosts anti-tumor immunity by inducing type I interferon production, which in turn promotes dendritic cell (DC) priming and T cell priming in the tumor microenvironment (TME)." (PMID 34625078, 2021). "The expression of cGAS and/or STING is recurrently suppressed by DNA hypermethylation in a variety of cancer cell lines, leading to an inability to activate the production of STING-dependent cytokines, important to suppress tumor development." (PMID 34341449, 2021). "Here we show that cytosolic DNA present in many tumor cells, but not normal healthy cells, activates the cGAS/STING pathway." (PMID 33790360, 2021).
tumor (continued). "RT-induced micronuclei activate cytosolic nucleic acid sensor pathways, such as cyclic GMP-AMP synthase (cGAS)-stimulator of interferon genes (STING), and propagation of the resulting inflammatory signals remodels the immune contexture of the tumor microenvironment." (PMID 34094967, 2021). "In addition to destroying tumor cells to release antigens for enhanced antigen presentation, radiotherapy also enhances anti-tumor immunity by upregulating MHC-I expression and the cGAS-STING pathway, increasing TCR density and the abscopal effect." (PMID 34858835, 2021). "Another problem worthy of study is whether regulating cGAS-STING in TAMs can prevent chronic inflammation and facilitate anti-tumor function." (PMID 34207286, 2021). "Furthermore, it has been shown that Mn2+ is a second cGAS activator besides dsDNA and acts in the activation of the cGAS-STING pathway, further activating tumor immunity via mediating DCs maturation." (PMID 34656118, 2021). "Likewise, through any immunotherapy, regulating the cGAS–STING immune pathway for therapeutic use depends on initiating a robust antitumor immune response, yet limiting tumor‐advancement." (PMID 32195086, 2020). "It has been demonstrated that nuclear cGAS is recruited to double-stranded breaks and interacts with PARP1 via poly(ADP-ribose), leading to suppression of homologous recombination and thereby promotion of tumor growth." (PMID 32474700, 2020). "Unexpectedly, the cGAS-STING signaling pathway and inflammation have pro-tumor functions." (PMID 32887628, 2020). "Being a basic inducer of IFN reactions, it is not unexpected that cGAS–STING can similarly advance tumor inception and development in a phase‐oriented way." (PMID 32195086, 2020). "Similarly, the administration of topotecan, an inhibitor of topoisomerase I, in E0771 murine breast cancer cells leads to the release of immunogenic DNA that induced cGAS-STING-dependent signaling, thereby driving anti-tumor immunity." (PMID 32774773, 2020). "Hence, in this review, we summarize the mechanism of cGAS-STING activation and elaborate findings regarding its dual effects on tumor development." (PMID 32854711, 2020). "Recently, studies revealed that self-DNA from by-products of chromosome instability and tumors could activate the cGAS-STING pathway, and subsequently promote or inhibit tumor development." (PMID 33006365, 2020). "The immunostimulatory potential of the cGAS-STING pathway makes it an attractive pharmacological target, since its activation in the tumor microenvironment (TME) can induce efficient cross-priming of tumor-specific antigens and facilitate the infiltration of effector T cells." (PMID 32854711, 2020). "Like inflammation generated by cGAS-STING, a time-dependent inflammatory anti-tumor response mediated by cGAS-STING may be present." (PMID 32411126, 2020). "Current studies demonstrated that type I IFN-dependent anti-tumor effect after radiation is mediated by the cGAS-STING pathway, rather than the TLR pathway." (PMID 32887628, 2020). "Contaminating stromal cells may mask the actual expression of cGAS-STING, or this difference reflects both pro-tumor and anti-tumor roles of cGA-STING in specific tumor types." (PMID 32571374, 2020). "To directly assess whether 2′3′-cGAMP generated from tumor cells could activate STING in endothelial cells, we next generated cGAS knockout H1355 cells and treated them with poly(dA:dT)." (PMID 33013881, 2020). "When DSBs occur in cancer cells, cGAS can be relocated to the nucleus and obstruct the formation of the PARP1-Timeless complex, thereby inhibiting homologous recombination repair and maintaining CIN, which potentiates tumor evolution." (PMID 32411126, 2020). "In addition to the cGAS-STING pathway, it was reported that activation of RIG-I signaling pathway in breast cancer cells also enhanced tumor growth, metastasis, and therapy resistance." (PMID 33633744, 2020).
tumor (continued). "Our system of Sting knockout tumors hosted in mice with a Sting/cGas wild-type background allowed us to not neglect the tumor-extrinsic function of Sting in APCs, that are likewise able to “sense” viral DNA." (PMID 33213060, 2020). "Together, cGAMP, as cGAS-STING pathway agonist, has versatile applications in anti-tumor immunity." (PMID 32887628, 2020). "A promising approach involves upregulation of the cyclic guanosine monophosphate-adenosine monophosphate synthase-stimulator of interferon (IFN) genes (cGAS-STING) pathway, a major component of the innate immune system involved in antiviral and anti-tumour immunity." (PMID 33081170, 2020). "However, cGAS expression and type I IFN production are simultaneously muted by miR-25/93, leading to the suppression of CD8+ T cell-mediated anti-tumor immunity and the establishment of an immunosuppressive environment with Treg and MDSC recruitment." (PMID 32774773, 2020). "We also discuss adaptive mechanisms used by cancer cells to circumvent cGAS-STING signaling and present evidence linking chronic cGAS-STING activation to inflammation-induced carcinogenesis, cautioning against the use of activating the cGAS-STING pathway as an anti-tumor immunotherapy." (PMID 32774773, 2020). "Furthermore, cGAS plays a role in human keratinocytes sensing of HSV-1 and VACV and the anti-tumor response in stromal cells." (PMID 31877196, 2019). "However, due to shortage of tumor-specific T cells or inadequate activation of STING protein, cGAS-cGAMP-STING pathway can be suppressed in some serve diseases, such as infection and cancer." (PMID 31120925, 2019). "While the activation of cGAS-STING signaling in tumors might provide a powerful means to mobilize immune surveillance and thus lead to tumor clearance, CIN tumors will likely have adapted to sustained cGAS-STING signaling and thus have become insensitive." (PMID 31658669, 2019). "Also, tumor-derived MPs inducing the type-I interferons (through the cGAS/STING pathway) resulted in increased dendritic cell maturation, and in enhanced tumor specific T-cell tumor lysis." (PMID 30895170, 2019). "Recent studies revealed that damaged NAs released by dying cancer cells can be sensed as DAMP danger signals by PRRs present on CD8α dendritic cells (DCs) in tumor microenvironment (TME), leading to activation of cGAS-STING and/or RIG-I/MDA5 signaling pathways." (PMID 29686682, 2018). "The cGAS-STING signaling is also indispensable for the immune sensing of the immunogenic tumors, which ultimately induce the IFN-β production and activate dendritic cells, thus promoting the cross-priming of CD8+ T cells against tumor in vivo." (PMID 28095500, 2017). "Our data demonstrate that cGAS and STING expression, and function in the cancer cells are essential for optimal anti-tumour T cell induction by radiotherapy, suggesting their potential role as predictors of tumour response to combinations of radiation and immune checkpoint inhibitors." (PMID 28598415, 2017). "DNA sensing cGAS/STING activation by radiation and/or STING agonist promotes type I IFN production and signaling in dendritic cells, leading to increased priming of T cells and tumor control." (PMID 29170400, 2017). "To further investigate whether cGAMP targets the STING in the cGAS-cGAMP-STING-IRF3 pathway to facilitate antitumor activity, we examined the expression of STING and IRF3 in tumor tissues treated with cGAMP by immunofluorescence assay." (PMID 26754564, 2016). "Importantly, BODIPY-mediated phototherapy combined with immunotherapeutic strategies (immune checkpoint blockade, pyroptosis/cuproptosis induction, cGAS-STING activation, etc.)achieves synergistic antitumor effects, transforming localized tumor ablation into systemic immunity." (PMID 42318338, 2026).